EGFR (epidermal growth factor receptor)
Diseases named in the same sentence as EGFR in open-access papers (continued):
Sharing a sentence is not in itself a finding about the gene and the disease.
cancer (continued). "Our results may provide a new strategy for EGFR-driven cancer therapy, especially for EGFR-mutant cancers." (PMID 37240137, 2023). "Recently, the roles of EGFR in the development of human cancer have attracted increasing attention." (PMID 37305523, 2023). "The performed analyses allowed us to identify two compounds 15 and 18 showing improved inhibition of double mutant EGFR with respect to the original hit, as well as interesting antiproliferative activity against H1975 NSCLC cancer cells expressing double mutant EGFR." (PMID 36373202, 2023). "The EGFR-targeting ASOs studied so far were designed to target the translation-initiation or termination regions of EGFR, leading to translation blockade, and were reported to have inhibitory effects in different cancer cells." (PMID 38137520, 2023). "Furthermore, Dmel\ EGFR is orthologous to human gene ERBB2, which has also been implicated in multiple cancers." (PMID 36926584, 2023). "We focused on two of these pathways—Glycolysis and gluconeogenesis and Transmembrane transport of small molecules —because of their strong PTM cluster-based links to the EGF/EGFR signaling pathway and because of the importance of metabolic adaptations in the progression to advanced cancer." (PMID 36996232, 2023). "Such immunosuppressive TME could be explained by the tight regulation of important chemokines for the recruitment and the activation of immune cells in EGFR mutant cancer cells." (PMID 37180110, 2023). "Unlike chemotherapy, which can cause damage to healthy cells leading to adverse side effects, gefitinib specifically targets and inhibits the EGFR pathway that is often overexpressed in cancer cells, making it a more targeted therapy with potentially fewer side effects." (PMID 37310466, 2023). "AuNP-NmAb has great potential in the treatment of EGFR+ cancers." (PMID 37762316, 2023). "With further exploration of PET1, we might find that we have a new way to therapeutically target EGFR-mediated cancers that combats off-target effects and drug resistance." (PMID 37315787, 2023). "EGFR is a protein that is often overexpressed in cancer cells." (PMID 37376417, 2023). "For example, the tubulin inhibitors vincristine and vinblastine isolated from Catharanthus roseus are used in the treatment of various cancers, whereas dacomitinib is a well-known antitumor agent that blocks the activity of epidermal growth factor receptor (EGFR)." (PMID 37513830, 2023). "Furthermore, in these events, EGFR is also involved since it forms a complex with β-catenin and further promotes the cancer cell’s ability to invade and metastasize." (PMID 37763165, 2023). "In addition, DMEA revealed consistent results across all three input gene signatures for drug MOAs identified as potentially toxic for EGFR inhibitor-resistant cancer cell lines, including HMGCR and MDM inhibitors." (PMID 37226094, 2023). "EGFR and its family members, primarily HER2, are ubiquitously expressed in epithelia, including the epithelium of the lung, and they have been found to be overexpressed or mutated in several types of cancer." (PMID 37894376, 2023). "Therefore, the epidermal growth factor receptor (EGFR) still remains a crucial targetable transmembrane protein in cancer management known for its role in cell proliferation, survival, migration, adhesion, and differentiation." (PMID 37513936, 2023). "In contrast to aNSCLC patients with EGFR or ALK driver mutations, patients with KRAS G12C–positive cancer may benefit from CIT monotherapy." (PMID 37069542, 2023). "EGFR is often highly upregulated in cancer cells where it induces multiple signaling cascades that stimulate cell proliferation and angiogenesis, which lead to pathogenesis and the progression of cancer." (PMID 37623652, 2023). "Other critical nodes include AKT1, SRC, CTNNB1 and EGFR, which are related to cancer signalling." (PMID 36944690, 2023). "Specifically, EGFR upregulation induces various types of cancer and promotes Aβ pathology." (PMID 37601068, 2023).
cancer (continued). "It was shown that small molecular degraders based on allosteric EGFR-TKI selectively inhibit the proliferation of cancer cells carrying the EGFRL858R/T790M double mutant and the osimertinib-resistant triple mutants, EGFRL858R/T790M/C797S and EGFRL858R/T790M/L718Q." (PMID 37754201, 2023). "We also noticed that in cell lines treated singly with either crizotinib or foretinib, the pEGFR/EGFR ratio was elevated, which may indicate that the cancer cells compensate for the reduced pMET/MET ratio by increasing the pEGFR/EGFR ratio." (PMID 37679999, 2023). "As erlotinib is an EGFR TKI, it seems likely that the patients with an EGFR positive cancer genotype would benefit more from treatment with erlotinib than the patients with an EGFR wild type genotype, making it difficult to evaluate the actual effect of the added onartuzumab or capmatinib treatment." (PMID 37568643, 2023). "In the current study, we aimed to evaluate whether CD27 co-stimulation could be restricted to epidermal growth factor receptor (EGFR)-positive cancer (EGFR+)." (PMID 37545491, 2023). "CCN3 was found to induce cancer by interacting with the EGFR signaling pathway in TNBC." (PMID 36737605, 2023). "Preclinical data have shown the activity of a new ADC of REGN5093 conjugated to a novel maytansinoid M114 in EGFR+ NSCLC cancer cells refractory to EGFR-TKI." (PMID 37835473, 2023). "As we all know, the abnormal cardiomyocyte homeostasis induced by autophagy is essential for AIC occurrence, and EGFR tyrosine kinase inhibitor has been reported could induce autophagy in cancer cells." (PMID 37168657, 2023). "In addition, they found a beneficial effect of a combinatorial EGFR inhibition on organoid viability in RAS-mutated cancers, possibly providing an alternative treatment strategy for this subtype of cancer." (PMID 37189676, 2023). "Other methods of targeting KRAS-mutated cancers are using pan-pathway inhibitors, most commonly targeting the downstream MAPK molecule MEK, with enhanced efficacy with combination therapy targeting the EGFR, CDK, JAK/STAT, PI3K pathways with a KRAS inhibitor." (PMID 37190303, 2023). "Single-molecule tracking could be used as a tool to test for the presence of overexpression of EGFR in cancers." (PMID 37754956, 2023). "Epidermal growth factor receptor (EGFR) is a transmembrane tyrosine kinase receptor that showed “gain of function” in many cancers through different mechanisms such as receptor overexpression, mutations, ligand-dependent receptor dimerization and ligand-independent activation." (PMID 37511133, 2023). "Tendentiously, we surmised that PRV-LAV infects EGFR-overexpressing cancer cells." (PMID 37891570, 2023). "Survival meta-analysis showed that NUAK1, Akt isoforms (Akt1, Akt2, and Akt3), mTOR, and Rictor positively correlate with a high hazard ratio (HR) in BRCA, COAD, GBM, PRAD, STAD, and OV, the same types of cancer where NUAK1 correlates with EGFR expression and Akt Ser-473 phosphorylation." (PMID 38135881, 2023). "Moreover, EGFR, which induces the expression of hBD-3, is overexpressed in many cancer types, including OSCC." (PMID 36980171, 2023). "Notably, hyperactivated EGFR signaling was found in various cancer types that acquire cisplatin resistance." (PMID 37165076, 2023). "Eps8 is a substrate of EGFR and has been shown to be involved in regulating cancer progression." (PMID 37169593, 2023). "Regardless of the presence or absence of specific diagnostic mutations, many cancer patients fail to respond to EGFR-targeted therapeutics, and a personalized approach is needed to identify putative (non)responders." (PMID 37626832, 2023). "Resistance to EGFR inhibition presents a significant challenge in cancer therapeutics." (PMID 36977662, 2023). "EGFR has been found to be overexpressed in many cancer cells." (PMID 38005329, 2023). "Interestingly, treatment with svPLA2s in cancer cells with a high EGFR density has affected their viability." (PMID 38067143, 2023).
cancer (continued). "Importantly, an increasing menu of highly CNS-active targeted therapies including for EGFR-variant and ALK-rearranged malignant neoplasms allows a growing proportion of patients to avoid metastasectomy and/or brain radiation." (PMID 37906192, 2023). "The cancer-associated fibroblasts (CAFs) have been found to secrete hepatocyte growth factor (HGF), thereby instigating resistance to pharmacological interventions targeting tyrosine kinases and the epidermal growth factor receptor (EGFR)." (PMID 37666809, 2023). "The binding characteristics of selected G. glabra bioactive compounds (i.e., LTS0058805, LTS0114552, LTS0128805, LTS0174203,LTS0007447, and LTS0164690) concerning EGFR, have been thoroughly documented and merit further exploration for their potentialapplication in cancer management." (PMID 37808374, 2023). "CircEMB plays a critical role in promoting cancer via the miR-3184-5p/EGFR pathway, indicating that circEMB may serve as a therapeutic target for OSA." (PMID 36611218, 2023). "Indeed, overexpression of these receptors, mutation, evasion of degradation, enhanced recycling, and/or altered signaling pathways of EGFR results in cancer development through enhancing downstream signaling." (PMID 37752992, 2023). "Keeping in mind our findings showing an impact of the SMN on E-cadherin expression, it is plausible to suppose that the SMN might operate at the crosstalk between the EGFR and E-cadherin, thus affecting tissue morphogenesis and cancer progression." (PMID 36675308, 2023). "Although aberrant EGFR activation through EGFR gene amplification and/or mutation has been detected in various types of cancer, this is not frequently found in HCC." (PMID 38138981, 2023). "Similarly, the knockdown of ATG7 or Beclin1 or treatment with CQN sensitized cancer cells to epidermal growth factor receptor blocking antibody (Cetuximab) and increased apoptosis." (PMID 37761021, 2023). "Our analysis suggests the hypothesis that other proteins that also appear as links between EGF/EGFR and our focus pathways could be candidates for drugs that can be used in combination therapy for cancer." (PMID 36996232, 2023). "Right-sided cancers are associated with higher rates of microsatellite instability (MSI), more frequent aberrant activation of the EGFR pathway including higher BRAF and PIK3CA mutation rates, and increased mutational burden compared to cancers in other locations." (PMID 38062443, 2023). "In addition, some molecules involving the three scaffolds; pyrazole, thiazole, and naphthalene, were reported to have notable anti-cancer activity targeting EGFR." (PMID 37291635, 2023). "In contrast, our studies showed that targeting GRP78 can suppress EGFR expression irrespective of their mutational or amplification status, thus potentially overcoming such therapeutic limitation in cancer treatment." (PMID 37487081, 2023). "Additionally, MET gene amplification leads to the upregulation of cMet, and the subsequent pathway allows cancer cells to bypass EGFR signaling for cell survival, thereby creating another avenue of resistance to our current EGFR-targeted treatments." (PMID 37370772, 2023). "For example, EGFR-mutated NSCLC is known to be especially sensitive to treatment with EGFR TKIs; and these TKIS are therefore often a first line treatment for this cancer." (PMID 37114134, 2023). "For instance, a high-throughput RNA inference screen of multiple cancer cell lines identified EGFR activation could be an escape mechanism to FGFR inhibition in FGFR3 mutant cancer." (PMID 37173994, 2023). "Epidermal growth factor receptor (EGFR), one of the growth factor-binding receptors, has been demonstrated to be overexpressed in multiple epithelial human cancer cells that served as a bull’s-eye for cancer drug delivery." (PMID 36839920, 2023). "This treatment strategy has been defined anti‐EGFR rechallenge and is based on the biological hypothesis of the dynamic evolution of cancer cell clones during treatment." (PMID 36880426, 2023).
cancer (continued). "CSF ctDNA could provide a more comprehensive genetic landscape of LM, which reveals the potential metastasis-related mechanisms of malignant tumours and the resistance mechanisms to EGFR-TKIs and guides clinical strategies." (PMID 37897649, 2023). "Many therapeutic efforts with Ab–NPs focus on cancer and on improving survival in vivo, by targeting EGFR, CD44, mucin 1 C terminus, HER2 (which are overexpressed in a variety of cancers such as breast and lung cancers), and death receptor 5 (which are overexpressed in pancreatic cancer)." (PMID 37849659, 2023). "Moreover, proanthocyanidins decreased the expression of epidermal growth factor receptor (EGFR), which is involved in cancer proliferation, migration, invasion, and angiogenesis." (PMID 36986152, 2023). "The combined data showed that GFP-EGF could play the role of natural EGF in cancer cells by mediating the phosphorylation of EGFR." (PMID 36611158, 2023). "Leucine-rich repeats and immunoglobulin-like domains protein 1 (LRIG1) is important in cancer development as it negatively regulates the epidermal growth factor receptor (EGFR); however, the mechanism responsible for this particular risk SNP and its potential effect on LRIG1 are not known." (PMID 37185361, 2023). "EGFR also interacts with the Hippo pathway in cancer development." (PMID 37665055, 2023). "In cancers, EGFR was found to be elevated and promoted several solid malignant tumors." (PMID 36893122, 2023). "What’s particularly noteworthy is that tumors undergoing transformation to SCLC maintain the original activating EGFR mutation, indicating a direct evolutionary process from the initial cancer rather than the emergence of a separate, secondary primary cancer." (PMID 38188289, 2023). "FAM83A gene enabled identical protein binding activity, phosphatidylinositol 3-kinase regulatory subunit binding activity, and protein kinase binding activity, which are involved in cancer cell population proliferation and the epidermal growth factor receptor (EGFR) signaling pathway." (PMID 37476189, 2023). "In addition, EGFR interacts with hormones in the human body to promote the occurrence and development of cancer." (PMID 38107059, 2023). "Second, the effective concentration of administered EGFR-TKI was relatively high in the ex vivo 3D cancer model compared to 2D cultures, which could correlate with the good survival observed among cancer cells implanted in bioengineered lungs." (PMID 37434755, 2023). "Previous studies showed that an increased EGFR expression was related to many cancer types." (PMID 36770659, 2023). "Resistance to ALK inhibitors may arise through EGFR signalling, and perhaps these cancer cells could also evade immune detection by downregulating EML4‐ALK." (PMID 37795653, 2023). "We therefore investigated the effect of EGFR co-targeted therapy with HER2 on patient-derived cancer models with the HER2 extracellular domain mutation E401G, based on our previous findings that this mutation has an epidermal growth factor receptor (EGFR)-mediated activation mechanism." (PMID 36690964, 2023). "The loss of miR-146a-5p may enhance epithelial-mesenchymal transition (EMT), thereby accelerating the metastasis of cancer cells by regulating the epidermal growth factor receptor (EGFR)/ERK pathway." (PMID 36594094, 2023). "Importantly, the promising role of phytochemicals in the modulation of pathways controlled by ER and EGFR was also demonstrated in several types of cancer." (PMID 36982173, 2023). "In previous reports, Akt activation was found to increase the activity of A Disintegrin and Metalloproteinase 17 (ADAM17), which increases the shedding of heparin-binding EGF (HB-EGF) and amphiregulin (AREG) from the cancer cell surface, leading to EGFR activation." (PMID 37779142, 2023). "This may be a turning point in the discovery of novel Cannabis sativa L-based drugs that specifically target cancers brought on by the overexpression of EGFR." (PMID 37128337, 2023).